TM4SF19 (transmembrane 4 L six family member 19)
Description:
Negatively regulates vacuolar (H+)-ATPase (V-ATPase) activity by interacting with members of V-ATPase V0 complex and hence inhibiting V1-V0 complex assembly. Required for multinucleation during osteoclast differentiation.
Synonyms: OCTM4
Tractability: Antibody: UniProt predicts a signal peptide or a membrane-spanning region.
Gene: Protein-coding gene on chromosome 3 (196,319,342 to 196,338,503, reverse strand). Ensembl gene ENSG00000145107.
Subcellular location: Lysosome membrane; Cytoplasm, cytoskeleton; Cell projection, filopodium
Gene Ontology:
Molecular function: protein binding; protein homodimerization activity
Biological process: positive regulation of osteoclast differentiation
Cellular component: actin cytoskeleton; filopodium; lysosomal membrane; membrane; cytoskeleton
Genetic constraint (gnomAD): Loss-of-function variants: 17 observed, 23.15 expected, observed/expected ratio (o/e) 0.73, 90% interval 0.5 to 1.1. The upper end of that interval is the gene's LOEUF score, 1.1, which puts it in group 4 of 6, group 1 being the genes least tolerant of losing a copy. Missense variants: 216 observed, 265.2 expected, observed/expected ratio (o/e) 0.81, 90% interval 0.73 to 0.91. Synonymous variants: 107 observed, 112.54 expected, observed/expected ratio (o/e) 0.95, 90% interval 0.81 to 1.12.
Homologues: Orthologues: macaque TM4SF19 (94% identical), pig TM4SF19 (83% identical), dog TM4SF19 (82% identical), rabbit TM4SF19 (82% identical), mouse Tm4sf19 (78% identical), chimpanzee TM4SF19 (76% identical), guinea pig TM4SF19 (76% identical), rat Tm4sf19 (76% identical), zebrafish si:dkey-83h2.3 (33% identical). Paralogues in human: TM4SF5 (32% identical), TM4SF1 (30% identical), TM4SF4 (28% identical), TM4SF18 (25% identical), TM4SF20 (23% identical).
Diseases named in the same sentence as TM4SF19 in open-access papers:
TM4SF19 is named in the same sentence as 18 diseases in open-access papers, as found by Europe PMC text mining. Sharing a sentence is not in itself a finding about the gene and the disease. The quoted sentences say what the papers report.
glioma (2 papers, 2020 to 2021). A benign or malignant brain and spinal cord tumor that arises from glial cells (astrocytes, oligodendrocytes, ependymal cells). "The other well-predicted genes, including COL5A1, CPA4, CSTB, and PPIC in gliomas and DAK, ITPRIP, TM4SF19, TMEM200A in RCC have not been studied thoroughly in cancer and their roles in cancer worth further investigating." (PMID 32194984, 2020).
Arthritis (1 paper, 2025). Inflammation of a joint. "In this study, we confirmed that Tm4sf19 is predominantly expressed in arthritis tissue-induced synovial macrophages." (PMID 40128226, 2025). "tm4sf19 mRNA in ADSM was higher than in normal tissue-derived synovial macrophages (NDSM), in arthritis tissue-derived synovial fibroblasts (ADSF) and in normal tissue-derived synovial fibroblasts (NDSF)." (PMID 40128226, 2025).
endometrial cancer (1 paper, 2023). Primary or metastatic malignant neoplasm involving the endometrium (mucous membrane that lines the endometrial cavity). "However, there have been no reports on the involvement of PRMT2, NEK6, NACC1, ATP2A2, and TM4SF19 in endometrial cancer." (PMID 37780629, 2023).
Hyperinsulinemia (1 paper, 2024). An increased concentration of insulin in the blood. "Global TM4SF19 KO also corrected HFD-induced hyperinsulinemia and hyperlipidemia (TG and cholesterol)." (PMID 38555350, 2024).
Insulin resistance (1 paper, 2024). Increased resistance towards insulin, that is, diminished effectiveness of insulin in reducing blood glucose levels. "Our snRNA-seq analysis demonstrates that Tm4sf19 KO reverses insulin resistance in adipocytes." (PMID 38555350, 2024).
liver fibrosis (1 paper, 2024). "TM4SF19, also known as OCTM4, was recognized to be associated with liver fibrosis and carcinomas." (PMID 38206300, 2024).
Obesity (1 paper, 2024). Accumulation of substantial excess body fat. "As TREM2+ macrophages have been implicated in pathophysiological tissue remodeling involving aberrant lipid metabolism, our results indicate that TM4SF19 might be targeted for treating a large class of obesity-associated metabolic diseases." (PMID 38555350, 2024). "Further investigation is required to fully understand the multiple molecular mechanisms of Tm4sf19 KO-mediated beneficial effects on obesity-induced inflammation and metabolic dysfunction." (PMID 38555350, 2024). "As anticipated, TM4SF19 knockout expedites the clearance of dead fat cells, protecting against obesity-induced inflammation and metabolic dysfunction." (PMID 38555350, 2024).
osteoporosis (1 paper, 2025). A condition of reduced bone mass, with decreased cortical thickness and a decrease in the number and size of the trabeculae of cancellous bone (but normal chemical composition), resulting in increased fracture incidence. "We previously demonstrated that the large extracellular loop (LEL) of Tm4sf19 is important for its function in osteoclast differentiation, and LEL-Fc, a competitive inhibitor of Tm4sf19, effectively suppresses osteoclast multinucleation and prevent bone loss associated with osteoporosis." (PMID 40128226, 2025).
Pancytopenia (1 paper, 2017). An abnormal reduction in numbers of all blood cell types (red blood cells, white blood cells, and platelets). "Most of the genes from day 1 appeared 2-fold downregulated (e.g., CDCA7L or GBP2), but three were 3–5-fold upregulated (C11orf96, GLUL, TM4SF19) relative to H0 when developing a HARS without pancytopenia." (PMID 28236054, 2017).
vitiligo (1 paper, 2023). Generalized well circumscribed patches of leukoderma that are generally distributed over symmetric body locations and is due to autoimmune destruction of melanocytes. "We noted that other genes, such as Lnc-ARRDC3-1, PLCG1, A_33_P3229958, TERM1, and RAB13, showed increased expression, whereas TM4SF19, IFI27, and IL17RB showed decreased expression in T cells from patients with vitiligo compared with the controls." (PMID 37731844, 2023).
cancer (4 papers, 2020 to 2024). A tumor composed of atypical neoplastic, often pleomorphic cells that invade other tissues. "Expression Atlas revealed that TM4SF1, TM4SF4, TM4SF18, and TM4SF19 were expressed in various cancer cell lines." (PMID 38206300, 2024). "More important, this group of genes also included genes whose roles in cancer have yet to be fully addressed (e.g., TM4SF1, TM4SF19, EMP1, PHLDA1, and PHLDA2)." (PMID 35831322, 2022).
tumor (2 papers, 2013 to 2024). "Immunoglobulin heavy constant gamma 1 (IGHG1) and transmembrane 4 L six family member 19 (TM4SF19) were related to tumor immune invasion mechanisms and then made the tumor cells immunity." (PMID 23577100, 2013).
TM4SF19 also shares sentences with these, for which no sentence is quoted: atherosclerosis (1 paper); gastric carcinoma (1); hepatocellular carcinoma (1); hyperlipidemia (1); inflammatory bone diseases (1); rheumatoid arthritis (1).